RPL35AP31 (ribosomal protein L35a pseudogene 31)
Gene: Processed pseudogene on chromosome 13 (71,845,981 to 71,846,317, forward strand). Ensembl gene ENSG00000233460.
Diseases named in the same sentence as RPL35AP31 in open-access papers:
RPL35AP31 is named in the same sentence as 1 disease in open-access papers, as found by Europe PMC text mining. Sharing a sentence is not in itself a finding about the gene and the disease. The quoted sentences say what the papers report.
prostate carcinoma (1 paper, 2024). A carcinoma that arises from epithelial cells of the prostate gland. "Among differentially methylated loci between adjacent benign tissue and PCa, a CpG site associated with the gene RPL35AP31 was found, which to date has not yet been described in the context of prostate cancer." (PMID 39180680, 2024).